SRRM2 (serine/arginine repetitive matrix 2)
Description:
Required for pre-mRNA splicing as component of the spliceosome. As a component of the minor spliceosome, involved in the splicing of U12-type introns in pre-mRNAs (Probable).
Synonyms: KIAA0324; SRL300; SRM300; HSPC075; Cwc21; 300-KD; CWF21; MRD72
Tractability: Small molecule: a structure with a bound ligand is known. PROTAC: UniProt records ubiquitination sites on it; ubiquitination databases record sites on it; its protein half-life has been measured.
Gene: Protein-coding gene on chromosome 16 (2,752,626 to 2,772,538, forward strand). Ensembl gene ENSG00000167978.
Subcellular location: Nucleus; Nucleus speckle
Subcellular location (Human Protein Atlas): Nuclear speckles
Pathways (Reactome):
Metabolism of RNA: mRNA Polyadenylation; mRNA Splicing - Major Pathway
Disease: Dengue Virus-Host Interactions
Gene Ontology:
Molecular function: C2H2 zinc finger domain binding; protein binding; RNA binding; mRNA binding
Biological process: mRNA splicing, via spliceosome
Cellular component: Cajal body; catalytic step 2 spliceosome; nuclear speck; nucleus; post-spliceosomal complex; spliceosomal complex; U12-type catalytic step 2 spliceosome; U2-type catalytic step 1 spliceosome; U2-type catalytic step 2 spliceosome; U2-type precatalytic spliceosome; nucleoplasm
Genetic constraint (gnomAD): Loss-of-function variants: 29 observed, 215.69 expected, observed/expected ratio (o/e) 0.13, 90% interval 0.099 to 0.18. The synonymous counts are far from expectation, so gnomAD's model fits this gene poorly and the ratio says little. Missense variants: 4,882 observed, 3,787.1 expected, observed/expected ratio (o/e) 1.29, 90% interval 1.26 to 1.32. Synonymous variants: 2,016 observed, 1,434.1 expected, observed/expected ratio (o/e) 1.41, 90% interval 1.35 to 1.46.
Homologues: Orthologues: macaque SRRM2 (98% identical), chimpanzee SRRM2 (97% identical), dog SRRM2 (91% identical), pig SRRM2 (89% identical), rat Srrm2 (87% identical), mouse Srrm2 (86% identical), rabbit SRRM2 (86% identical), guinea pig SRRM2 (85% identical), tropical clawed frog srrm2 (30% identical). Paralogues in human: MUC12 (21% identical).
Diseases named in the same sentence as SRRM2 in open-access papers:
SRRM2 is named in the same sentence as 50 diseases in open-access papers, as found by Europe PMC text mining. Sharing a sentence is not in itself a finding about the gene and the disease. The quoted sentences say what the papers report.
Alzheimer disease (8 papers, 2021 to 2025). A progressive, neurodegenerative disease characterized by loss of function and death of nerve cells in several areas of the brain leading to loss of cognitive function such as memory and language. "Phosphorylated nuclear speckle (NS) scaffold protein SRRM2 is mislocalized in Alzheimer’s disease, and the mislocalization of SRRM2 is correlated with the severity of pathological tau deposition." (PMID 37621647, 2023). "Recent studies have linked nuclear speckle dysregulation to Alzheimer’s disease, with SRRM2 miss-localized to the cytoplasm of brain tissue in Alzheimer’s disease patients." (PMID 36203874, 2022). "FOXA2 and SRRM2 are potential biomarkers for yolk sac tumors and Alzheimer’s disease." (PMID 41013561, 2025).
Parkinson disease (8 papers, 2010 to 2025). A progressive degenerative disorder of the central nervous system characterized by loss of dopamine producing neurons in the substantia nigra and the presence of Lewy bodies in the substantia nigra and locus coeruleus. "In previous studies, changes of SRRM2 variants were reported to be closely related with Parkinson’s disease." (PMID 38735973, 2024). "The scaffold protein SRRM2 is overexpressed in the brain and blood of people with Parkinson’s disease and is necessary to establish nuclear speckles and mRNA splicing." (PMID 37628788, 2023). "We observed significant down-regulation of SRRM2 (p = 0.0002) and miR-27a-3p (p = 0.0001), and up-regulation of miR-27b-3p (p = 0.02) in PBMCs of Parkinson's patients." (PMID 33171483, 2020). "Among this group, is the serine/arginine repetitive matrix 2 (SRRM2), a splicing factor with altered expression in blood and the substantia nigra of Parkinson's disease patients." (PMID 24376773, 2013). "As an illustration, an aberrant relative abundance of alternatively spliced RNA isoforms of the SNCA, SRRM2, DAO, SHANK3, CACNA1C, and TSC2 genes has been observed in the brains of patients suffering from amyotrophic lateral sclerosis, autism spectrum disorder, and Parkinson’s disease." (PMID 39858933, 2025).
Intellectual disability (5 papers, 2018 to 2026). "SRRM2-related neurodevelopmental disorders present with clinical features of mild developmental delay, intellectual disability, speech delay, generalized hypotonia, weight gain, and facial malformations." (PMID 40046925, 2025). "SRRM2 deficiency in neurons destabilized polyglutamine binding protein 1 (PQBP1), a causative gene for intellectual disability (ID), greatly affecting the splicing patterns of synapse-related genes, as demonstrated in a newly generated PQBP1-conditional knockout model." (PMID 30283027, 2018). "For instance, SRRM2 (MIM: 606032) was not included in this list despite good evidence for a role in intellectual disability via HI,53,54 and we note that three participants with deletion-inversions (likely palindrome-mediated) involving this gene were identified recently in the 100kGP." (PMID 38776926, 2024).
papillary thyroid carcinoma (5 papers, 2015 to 2022). "Patients carrying the SRRM2 missense genetic variant exhibited mis-splicing in specific cassette exons, while the variant segregated with familial papillary thyroid carcinoma." (PMID 36006412, 2022). "Through influencing the alternative splicing of downstream genes, the S346F mutation in serine/arginine repetitive matrix 2 (SRRM2) promotes the susceptibility of papillary thyroid carcinoma." (PMID 32117736, 2020). "A germline mutation in SRRM2 is related to the predisposition of papillary thyroid carcinoma." (PMID 32079071, 2020).
developmental delay (3 papers, 2023 to 2025). "The clinical presentation of SRRM2-related neurodevelopmental disorder is characterised by a mild developmental delay, occasionally associated with features of autism spectrum disorder (ASD) and/or attention-deficit/hyperactivity disorder (ADHD)." (PMID 40545495, 2025). "This individual was therefore suspected to have a blended phenotype linked to variants in three different genes, with the SRRM2 deletion helping to explain the developmental delay and dysmorphic features that had not been accounted for by the first two genes." (PMID 40225164, 2023).
nasopharyngeal carcinoma (3 papers, 2020 to 2025). A carcinoma arising from the nasopharyngeal epithelium. "SRRM2 is upregulated in colon adenocarcinoma, predicting poor prognosis, and its silencing inhibits angiogenesis in nasopharyngeal carcinoma through MYLK-mediated cGMP-PKG signaling pathway." (PMID 41013561, 2025). "SRRM2 overexpression has been observed in nasopharyngeal carcinoma, and its silencing in cellular models of the disease diminishes proliferation, blocks the cell cycle, and enhances apoptosis." (PMID 37422594, 2023).
Obesity (3 papers, 2025). Accumulation of substantial excess body fat. "Adding to this, we excluded a girl with a pathogenic SRRM2 variant because her BMI was just below the obesity threshold (96th percentile)." (PMID 40523925, 2025). "The association between SRRM2 missense mutations and obesity phenotypes is further supported by data from the UK Biobank PheWAS14." (PMID 40046925, 2025). "As discussed, patient #24 in this study carried a variant in SRRM2, which typically causes an intellectual developmental disorder and obesity." (PMID 40523925, 2025). "This unusual phenotypic expression of SRRM2 loss-of-function emphasizes the heterogeneity that can complicate the correct diagnosis of monogenic obesity." (PMID 40523925, 2025). "This large-scale population study revealed a strong correlation between SRRM2 missense variants and increased body weight and obesity-related traits." (PMID 40046925, 2025). "The third most frequently affected loci in patients with monogenic obesity in this cohort were PHIP and SRRM2, each impacted in three individuals." (PMID 40523925, 2025).
tauopathy (3 papers, 2021 to 2024). Neurodegenerative disorders involving deposition of abnormal tau protein isoforms (tau proteins) in neurons and glial cells in the brain. "Several studies have shown that tau immunopurifies with several RNA-binding proteins, and recent work has nominated nuclear speckles as a participant in tauopathies through the scaffold protein SRRM2." (PMID 34187600, 2021). "Guided by findings from molecular genetic investigations in model systems, the current study examines the impact of pathological tau on SRRM2 protein in the brains of AD patients and mouse models of tauopathy." (PMID 34187600, 2021). "Examination of the transcriptome and proteome of SRRM2 + /tau deposits and nuclear speckles in AD remain important future directions for our work investigating the molecular mechanisms of tauopathy disorders and will inform future molecular dissection of tau pathobiology." (PMID 34187600, 2021). "Furthermore, progression of tauopathy in transgenic mice is accompanied by increasing mislocalization of SRRM2 from the neuronal nucleus to the soma." (PMID 34187600, 2021). "Investigation of a small number of human tauopathy cases demonstrated mislocalization of SRRM2 in AD, but did not document the presence of nuclear tau/RNA assemblies." (PMID 34187600, 2021).
thyroid cancer (3 papers, 2016 to 2024). "Although the role of SRRM2 alternative splicing has yet been uncovered in cancers, its aberrant expression and germline mutation was found to contribute to thyroid cancer progression and recurrence." (PMID 38735973, 2024).
autism (2 papers, 2023 to 2025). Persistent deficits in social interaction and communication and interaction as well as a markedly restricted repertoire of activity and interest as well as repetitive patterns of behavior. "SRRM2 is known to be highly expressed in the brain and control RNA splicing patterns of multiple pre-mRNAs linked to autism." (PMID 40950074, 2025). "Two genes (SRRM2 and AKAP11) were newly implicated as SCZ risk genes, and one gene (PCLO) was identified as shared by individuals with SCZ and those with autism." (PMID 36914870, 2023).
Cognitive impairment (2 papers, 2018 to 2023). Abnormal cognition is characterized by deficits in thinking, reasoning, or remembering. "Here, we showed that SRRM2 phosphorylation at Ser1068 increases at the early stage of AD pathology associated with the translocation of SRRM2 to the cytoplasm, destabilizes the spliceosome component PQBP1, broadly affects RNA splicing of synapse genes, and eventually leads to cognitive impairment." (PMID 30283027, 2018).
schizophrenia (2 papers, 2022 to 2025). A major psychotic disorder characterized by abnormalities in the perception or expression of reality. "We meta-analyzed large-scale brain transcriptomic data from mice harboring individual loss-of-function mutations in seven schizophrenia risk genes (Akap11, Dagla, Gria3, Grin2a, Sp4, Srrm2, Zmym2)." (PMID 41022686, 2025). "Additional proteins with schizophrenia rare variant associations (via the SCHEMA consortium) altered in 22q11.2del neurons included DNM3, MAGI2 and TRIO (downregulated in patient neurons) and HIST1H1E, SRRM2 and ZMYM2 (upregulated in patient neurons)." (PMID 35760976, 2022). "Of particular interest, the Srrm2+/− and Dagla+/− mutants had a significant (FDR < 0.05) upregulation of the “response to dopamine” gene set in the striatum, including increased expression of Drd1 and Drd2, which are dopamine receptors highly relevant to schizophrenia." (PMID 41022686, 2025).
breast carcinoma (1 paper, 2021). "Previous workhas described how SRRM2 depletion in HER2-positive breast and ovariancancer cells reduced the rate of migration;55 the spliceosome plays myriad roles in the breast cancer environment,but site-specific analysis is lacking." (PMID 34164982, 2021).
chordoma (1 paper, 2023). Chordomas are rare malignant tumors arising from embryonic remnants of the notochord in axial skeleton. "Genes were selected to represent both those functionally connected to other chordoma dependency genes (PTPN11, FANCM, ADAR, PRKRA, SOX9, SRRM2, SLC2A1, and SLC7A5), as well as those with putatively unique effects (LUC7L2 and CDK6)." (PMID 37024492, 2023).
chronic heart failure (1 paper, 2023). "Since protein phosphorylation can alter the structure and activity of protein, we speculated that hyperphosphorylated Srrm2/Rnps1 might exacerbate post-infarction chronic heart failure through facilitating cargo export from nuclear pore." (PMID 37405054, 2023).
cognitive decline (1 paper, 2018). "PQBP1 and SRRM2 were downregulated in cortical neurons of human AD patients and mouse AD models, and the AAV-PQBP1 vector recovered RNA splicing, the synapse phenotype, and the cognitive decline in the two mouse models." (PMID 30283027, 2018).
dyscrasias (1 paper, 2024). "The expression of SRRM2 on plasma cells, granulocytes, monocytes, and lymphocytes was compared in each subgroup of plasma cell dyscrasias." (PMID 38289482, 2024).
endometriosis (1 paper, 2025). The growth of functional endometrial tissue in anatomic sites outside the uterine body. "We also suggest a link between FOXA2 and SRRM2 genes and this endometriosis form, recommending further research on gene mutations and molecular pathways for better diagnosis and understanding." (PMID 41013561, 2025). "Additionally, our study is the first to provide sequencing data, identifying FOXA2 and SRRM2 genes as associated with this form of endometriosis." (PMID 41013561, 2025). "The WES analysis indicated that FOXA2 and SRRM2 were respectively candidate driver genes for endometriosis in para-aortic lymph nodes and cystic adenomyosis requiring validation in larger cohorts and functional studies." (PMID 41013561, 2025).
frontotemporal dementia (1 paper, 2024). Frontotemporal dementia (FTD) comprises a group of neurodegenerative disorders, characterized by progressive changes in behavior, executive dysfunction and language impairment, as a result of degeneration of the medial prefrontal and frontoinsular cortices. "Interestingly, SRRM2 has been found to accumulate in neuron cytoplasm in Alzheimer’s disease (AD), frontotemporal dementia (FTD), and other neurodegenerative diseases." (PMID 39329747, 2024).
heart failure (1 paper, 2023). Inability of the heart to pump blood at an adequate rate to meet tissue metabolic requirements. "However, there is no single study on functions and mechanisms of phosphorylation of Srrm2/Rnps1 in heart failure." (PMID 37405054, 2023).
hepatoma (1 paper, 2024). "The same splicing alteration in PCYT2 was reported after SRRM2 depletion in the human hepatoma cell line HepG2." (PMID 38656788, 2024).
HIV-1 infection (1 paper, 2021). The type species of lentivirus and the etiologic agent of acquired immunodeficiency syndrome (AIDS). "Interestingly, altered SRRM2 phosphorylation has been also observed in HIV-1 infection." (PMID 33834021, 2021).
metastatic tumor (1 paper, 2025). "The results indicated that, compared to primary tumor tissues, the expression levels of PTBP3, RBFOX1, SRRM2, YBX3, and QKI were significantly higher in metastatic tumor tissues." (PMID 40270362, 2025).
mucopolysaccharidosis (1 paper, 2025). A group of autosomal recessive or X-linked inherited lysosomal storage disorders affecting the metabolism of mucopolysaccharides, resulting in the accumulation of mucopolysaccharides in the body. "Neurodevelopmental disorders related to SRRM2 exhibit significant similarities with other conditions, such as mucopolysaccharidosis heightening the risk of misdiagnosis." (PMID 40046925, 2025).
multiple myeloma (1 paper, 2024). "Serine/arginine repetitive matrix 2 (SRRM2) has been implicated in tumorigenesis, cancer development, and drug resistance through aberrant splicing; however, its correlation with multiple myeloma (MM) has not been reported." (PMID 38289482, 2024).
osteosarcoma (1 paper, 2019). A usually aggressive malignant bone-forming mesenchymal neoplasm, predominantly affecting adolescents and young adults. "Furthermore, SRRM2 knockdown in human osteosarcoma cells (U2OS) produced similar results." (PMID 31315647, 2019).
pancreatic cancer (1 paper, 2024). "Results from a first human xenograft model with pancreatic cancer cells and SRRM2-specific CAR-T cells corroborate the idea of SRRM2 as an attractive target molecule." (PMID 39329747, 2024).
plasma cell dyscrasias (1 paper, 2024). "The results showed that SRRM2 expression on plasma cells was significantly higher than that on normal blood cells in all subgroups, including MM, reactive plasmacytosis, and other plasma cell dyscrasias." (PMID 38289482, 2024). "In addition, in the reactive plasmacytosis group, 4 of the 7 samples were positive for SRRM2 expression on normal plasma cells, with a positive rate of 57.1%; 6 of the 8 samples in other plasma cell disorders were positive for SRRM2 expression on aberrant plasma cells, with a positive rate of 75%." (PMID 38289482, 2024).
viral infection (1 paper, 2022). "The previous studies on SRRM2 showed that it could interact with some viral proteins, increase nuclear permeability upon viral infection, and undergo differential phosphorylation following infection with HIV, leading to alteration of the host splicing machinery." (PMID 35154063, 2022).